IL10 (interleukin 10)
Diseases named in the same sentence as IL10 in open-access papers (continued):
Sharing a sentence is not in itself a finding about the gene and the disease.
melanoma (370 papers, 1994 to 2026). A malignant, usually aggressive tumor composed of atypical, neoplastic melanocytes. "To summarize, reactive microglia, synaptic loss, diminished myelin, higher number of inflammatory monocytes in the brain, and elevated plasma IL-10 in melanoma-bearing mice indicate cancer burden-associated changes compared to healthy control." (PMID 40313772, 2025). "To summarize, reactive microglia, synaptic loss, diminished myelin, higher number of inflammatory monocytes in the brain, and elevated plasma IL-10 in melanoma-bearing mice indicate cancer burden-associated changes compared to healthy controls." (PMID 40605058, 2025). "In the present study, we investigated the role of LPA-induced IL-10 release in regulating HLA-DR expression and the underlying mechanisms in human melanoma cells." (PMID 39187677, 2025). "In primary melanomas, tumor cell IL-10 mRNA content is associated with increasing Clark and Breslow thickness." (PMID 39825956, 2025). "Although the role of IL-10 in tumor biology is controversial, elevated serum levels of IL-10 are reportedly associated with a poor prognosis in melanoma." (PMID 39187677, 2025). "We found a statistically significant correlation between the expression of LPAR1, DR6 and IL-10 in human melanoma tissue and an association between increased expression of LPAR1 and reduced effectiveness of ICI therapy." (PMID 39187677, 2025). "These miRNAs were shown to inhibit the proliferation of IL-10-treated melanoma cells, while their inhibitors caused an increase in cell proliferation in melanoma (Ref." (PMID 38186186, 2024). "The xanthine derivative 16 decreases the quantity of tumor-associated CD11b+Gr-1+ cells within melanoma cells as well as the levels of immune regulatory mediators like interleukin-10 (IL-10) and monocyte chemoattractant protein 1 (MCP-1)." (PMID 39124905, 2024). "Of notice, both primitive and acquired resistance to targeted therapy have been associated with an increased capability of melanoma cells to produce both IL-6 and IL-10." (PMID 36765891, 2023). "This is the case of BRAF mutations in melanoma cells correlating with enhanced levels of immunosuppressive mediators such as IL-6 and IL-10 or anti-apoptotic Bcl-2 and Bcl-xL proteins, regulating the expression of several interleukins, such as IL-8 and IL-1β." (PMID 36768978, 2023). "Administration of an A2BR agonist had increased tumor growth in melanoma-bearing mice that was associated with increased accumulation of CD11b+Gr1+ MDSCs in the TME as well as higher levels of IL-10 and MCP-1." (PMID 37834375, 2023). "The hyperactivation of the β-catenin signalling pathway has been linked to elevated expressions of CTLA-4 and IL-10 in human melanomas, thereby establishing an immunosuppressive tumour microenvironment that favours tumour-cell proliferation." (PMID 36068277, 2022). "This approach is based on the observation that BRAF-mutated melanoma cells have a low T cell infiltration and a high level of IL-6, IL-10, and VEGF, which increase the number of Tregs or myeloid-derived suppressor cells within TME." (PMID 35334544, 2022). "In melanoma, IL-10 expression by tumor cells is associated with melanoma progression, while overexpression of serous IL-10 leads to an adverse survival in most cancer types." (PMID 35681689, 2022). "In melanoma, IL-10 expression by tumor cells associates with melanoma progression, and high serum IL-10 associates significantly with worse OS." (PMID 35255925, 2022). "We then determined the densities (cells/mm2) of each of the LTA+ and IL-10+ B cell subpopulations in the primary melanomas and their association with the most important categorical clinicopathologic parameters." (PMID 34359321, 2021). "IL-10-treated DCs have been shown to promote CTL anergy toward melanoma-specific antigens, resulting in a loss of cytolytic activity in vitro." (PMID 33401460, 2021).
melanoma (continued). "Melanoma differentiation associated gene-7/Interleukin-24 (MDA-7/IL-24) is a unique cytokine belonging to the IL-10 gene family that was cloned using subtraction hybridization in the early-nineties." (PMID 35008495, 2021). "IL‐10 gene polymorphisms that reduce IL‐10 levels correlate with increased melanoma incidence, while high IL‐10 levels are observed at sites of spontaneous rejection in primary melanoma, potentially NK cell mediated." (PMID 32578964, 2020). "Upregulation of the miR-30b/-30d cluster in melanoma cells is associated with a decreased level of GalNAc7 transferase and increased secretion of IL-10, which impairs the recruitment of effector T cells and enhances Treg infiltration." (PMID 33171792, 2020). "IL-19 is a member of the IL-10 family, which includes IL-10, IL-19, IL-20, IL-22, melanoma differentiation-associated gene (MDA)-7 (IL-24), and AK155 (IL-26)." (PMID 31114590, 2019). "Other tumor-generated immunosuppressive cytokines include interleukin 10 (IL-10), which reduces the action of melanoma-associated macrophages and lymphocytes." (PMID 31861163, 2019). "An example of a chemokine in the microenvironment that influences implantation and growth of metastasis is IL-10, which appears to render lymph nodes susceptible to metastasis through its action on melanoma-associated macrophages and lymphocytes." (PMID 31861163, 2019). "In melanomas, IL-10 was associated with metastatic formation, and TGF-β is highly expressed and increases in parallel with tumor progression." (PMID 31167479, 2019). "Employing lysates from IL-10 modulated DC precursors on a peptide kinase substrate microarray, we identified putative signaling networks at play in melanoma-associated DC suppression." (PMID 30400822, 2018). "Mechanistically, IL-10 has been found to be implicated in inhibition of the T-cell immune response and can act as an autocrine growth factor for melanoma cells, down-regulating the expression of HLA molecules to contribute to the immune escape." (PMID 29467923, 2018). "The IL-10-deficient B-1 lymphocytes were unable to induce alterations in the metastatic melanoma behavior, indicating that the IL-10 production by B-1 lymphocytes plays a pivotal role in the interplay between these cells." (PMID 29145406, 2017). "Collectively, these results indicate that HMGB1-dependent production of IL-10 by tumour-associated M2-like macrophages contributes to tumour progression in our mouse melanoma model." (PMID 27426915, 2016). "In accordance with this, elevated IL-10 production levels in melanoma patients are associated with poor prognosis." (PMID 27426915, 2016). "We found a significant association with melanoma OS for 2 independent genetic variants (rs3024493, r222202) in the interleukin locus at 1q32.1, mapping in the region of interleukin 10 (IL10)." (PMID 26597176, 2015). "Melanoma differentiation associated gene-7 (mda-7), also known as Interleukin-24 (IL-24), encodes a secreted protein of the IL-10 gene family and is located on chromosome 1q32-33 in humans." (PMID 26474456, 2015). "This is a critical gap in the understanding of the role of the IL-10/IL-10R system in melanoma, since α and β chains are encoded by distinct genes and display different role in triggering the signaling events." (PMID 26631117, 2015). "IL-10 has traditionally been considered an immunosuppressive cytokine, associated with more aggressive melanoma tumor progression." (PMID 26597176, 2015). "Further, we are confident that our study population is representative as we already identified DNA repair gene SNPs and interleukin 10 promoter polymorphisms as independent molecular melanoma risk factors with this study population." (PMID 22576141, 2012). "In melanoma patients IDO expression in SLN has been linked with the immunosuppressive cytokine IL-10." (PMID 19604349, 2009). "An association of IL-10-1082 AA promoter polymorphism with worst prognosis in melanoma is suggested and should be further investigated." (PMID 18221542, 2008).
melanoma (continued). "In melanoma, the AA genotype has been associated to a poorer prognosis, supporting the recent findings that IL-10 has an anti-tumor effect possibly via inhibition of angiogenesis." (PMID 18221542, 2008). "FOXp3-positive, IL-10 producing T lymphocytes were recently reported in tumour, blood and ascites from patients with advanced melanoma, and were associated with melanoma-related immunosuppression." (PMID 17565341, 2007). "Similar findings were reported before where IL-10 elevation was associated with inferior survival in stage IV melanoma patients, reinforcing the possibility that IL-10 may hold prognostic value as an early marker." (PMID 41020868, 2025). "Spatial transcriptomics analysis of micro-glial cells near melanoma demonstrates that there is a homeostatic-to-regenerative transition in micro-glial cells that is associated with increased levels of C3, IL-10, and TREM2 and reduced levels of CXCL10 and MHC-II." (PMID 41463339, 2025). "Elevated baseline levels of cytokines in melanoma patients have been mainly studied for IL-6 and IL-10, with elevated initial levels of IL-10 being associated with increased mortality, while a progressive increase in IL-6 predicts a worse prognosis in melanoma." (PMID 40004863, 2025). "As elevated IL-10 levels are frequently associated with poor prognosis in different cancer types, we aimed to examine the potential role of LPA-induced IL-10 release in regulating HLA-DR expression and clarify the underlying signaling mechanisms in human melanoma cells." (PMID 39187677, 2025). "Since IL-10 is associated with B-1 cells performance, we hypothesized that IL-10 could be implicated in the progression of melanoma." (PMID 29145406, 2017). "Here we show that the damage-associated molecular pattern High-Mobility Group Box 1 protein (HMGB1) is released by melanoma tumour cells as a consequence of hypoxia and promotes M2-like tumour-associated macrophage accumulation and an IL-10 rich milieu within the tumour." (PMID 27426915, 2016). "Melanoma differentiation associated gene-7/Interleukin-24 (MDA-7/IL-24) is a novel member of the IL-10 gene family that selectively induces apoptosis and toxic autophagy in a broad spectrum of human cancers, including breast cancer, without harming normal cells or tissues." (PMID 26474456, 2015). "Exogenous IL-10 was also shown to inhibit melanoma metastasis in mice that were deficient in B cells and T cells but with competent NK cells, suggesting that infiltrating NK cells may play a key role in suppressing metastatic spread." (PMID 26217588, 2015). "In addition, overexpression of IL-10 within tumors, in murine carcinoma and melanoma models, results in loss of tumorigenicity accompanied by an enhanced lymphocyte response." (PMID 23755052, 2013). "Polymorphism in the IL-10 promoter has been associated with differential in vitro secretion of IL-10, and various authors have reported that these polymorphisms may influence the outcome of melanoma patients." (PMID 18221542, 2008). "When the supernatant of this construct was added to a monocyte culture, increased levels of IL-10 could drive monocyte differentiation to tumor-associated M2-like macrophages, thus describing a novel mechanism of immune tolerance in melanoma and a possible therapeutic target to overcome it." (PMID 38136325, 2023). "Berberine-mediated STAT3 inhibition reduced IL-10 expression in melanoma cells; reprogrammed M2 tumor-associated macrophages to a tumorsuppressive M1 phenotype; increased tumor cell recognition by T cells; and ultimately reduced tumor burden in melanoma-bearing mice." (PMID 36700235, 2022). "Furthermore, monocytes treated with melanoma-patient-derived sera differentiated into macrophages, which also secreted higher levels of IL-10 compared to monocytes treated with sera from healthy donors, showing that this is a feature of melanoma-associated macrophages." (PMID 30712866, 2019).
melanoma (continued). "Similarly, the associations of eQTLs in IL-10 locus with melanoma progression may expand the applicability to immunotherapy with the concurrent targeting of IL-10 receptor during the treatment with ICI." (PMID 31113486, 2019). "Similarly, IL-10 is known to promote Socs3 gene expression, and melanoma-associated DC have been found to exhibit SOCS3-mediated inhibition of the M2 pyruvate kinase (PKM2) that catalyzes conversion of phosphoenolpyruvate into pyruvate in the final step of glycolysis." (PMID 29209327, 2017). "Additionally, SAA-1 could induce anti-inflammatory interleukin-10 (IL-10)-secreting neutrophils, which have been linked to the consequent promotion of melanoma progression." (PMID 22917173, 2012). "In melanoma, we identified an 8-gene signature (CD28, CD80, CD86, CTLA4, FAS, IFNG, IL10, and IL12A) associated with survival." (PMID 42216340, 2026). "IL-10 has been identified as a poor prognostic marker in many malignancies, including melanoma, lymphoma, and others." (PMID 41007766, 2025). "For example, senescent macrophages in aged melanoma‐bearing mice upregulate arginase‐1 and IL‐10, suppressing T cell activity and promoting Treg recruitment." (PMID 40926366, 2025). "Treatment of A2058 and A375 melanoma cells with 10 μM LPA increased IL-10 transcripts with a similar time course in both cell lines, resulting in maximal expression of IL-10 mRNA 3 h after LPA treatment." (PMID 39187677, 2025). "IL-10 overexpression is a key feature of aggressive and highly proliferative tumors, such as melanoma and colorectal cancer." (PMID 39841829, 2025). "In a B16F10 melanoma model, auranofin treatment increased lung tumor coverage, IL-10 serum levels, and FOXP3+CD44+CD4+ T cell frequencies." (PMID 41300507, 2025). "Several malignancies, including melanoma, squamous cell carcinoma, basal cell carcinoma, and lymphomas, have been shown to overexpress IL-10." (PMID 40630332, 2025). "The present study reveals a connection between the elevated LPA concentration and IL-10 production, which in turn diminishes the HLA-DR expression in melanoma." (PMID 39187677, 2025). "We also showed that the LPA-induced secretion of IL-10 in melanoma cells is mediated by LPAR1 and DR6." (PMID 39187677, 2025). "LPA (10 μM) significantly increased IL-10 transcripts in A2058 and A375 melanoma cells, the effect was abolished by pharmacological inhibition of LPAR1 or knockdown of DR6." (PMID 39187677, 2025). "Intriguingly, in melanoma cells, GALNT7 silencing was associated with increased IL-10 secretion, enhanced CTLA-4 expression, and the modulation of immune evasion." (PMID 40824763, 2025). "Strong inter-cytokine correlations were observed (NSCLC: TNF-α vs. IL-10, ρ = 0.60, 95% CI 0.19–0.82; melanoma: ρ = 0.93, 95% CI 0.44–0.99)." (PMID 41020868, 2025). "Melanoma patients exhibit more variable IL-10 patterns, with some patients showing inflated baseline levels that fluctuate during treatment." (PMID 41020868, 2025). "Melanoma cells can secrete immunosuppressive cytokines, including IL-10 and TGF-β, which impair the activity of immune cells such as T cells and NK cells." (PMID 40636453, 2025). "Although promising results have been seen in animal models, including the use of IL-10-expressing CAR T cells to overcome T cell dysfunction in solid tumors like melanoma, the efficacy of these approaches needs to be validated in human trials." (PMID 40376583, 2025). "IL-24, initially identified as melanoma differentiation-associated gene-7 or MDA-7, is an anticancer cytokine within the IL-10 gene family." (PMID 39782693, 2025). "For instance, melanoma-derived exosomes have been shown to induce macrophage polarization toward an M2-like phenotype, which in turn secretes interleukin-10 (IL-10) and transforming growth factor-beta (TGF-β) to suppress anti-tumor immunity." (PMID 41034991, 2025).
melanoma (continued). "In concordance, upregulation of both TGFβ and PD-L1 on B cells in advanced melanoma and expansion of IL-10+plasmablasts and TGFβ+PD-L1+ naïve B cells indicate regulatory response induction." (PMID 40449958, 2025). "Preclinical studies have shown that blocking IL‐10 or CSF1R in aged melanoma‐bearing mice can partially restore responsiveness to checkpoint blockade, underscoring the central role of myeloid dysfunction in therapeutic resistance." (PMID 40926366, 2025). "Recent animal research has shown that IL-10 antibodies can alleviate immune suppression and significantly enhance anti-tumor immunity in cancers such as melanoma and cervical cancer." (PMID 40292253, 2025). "Investigating the relationship between LPA-LPAR signaling and IL-10-HLA-DR expression represents a topic previously unexplored in melanoma research." (PMID 39187677, 2025). "In melanoma, triptolide inhibits melanoma growth by suppressing the generation of regulatory T cells and the production of several cytokines, such as IL-10, TGF-β, and vascular endothelial growth factor." (PMID 41458964, 2025). "Another contributing factor is the presence of tumor-associated macrophages (MDSCs), which secrete tumor-promoting cytokines such as nitric oxide (NO) and interleukin-10 (IL-10), accelerating melanoma progression and reinforcing resistance." (PMID 40141317, 2025). "Preclinical and clinical studies have demonstrated efficacy combined with radiation, high-dose IL-2, and IL-10 through the expansion of CD8+ T cells against melanoma and renal cell carcinoma." (PMID 38398104, 2024). "Evidence also shows that IL-10 can inhibit angiogenesis, as indicated by a study employing a mouse model of melanoma, in which melanoma cells that expressed IL-10 via a transfected viral vector exhibited an attenuation of tumor growth and metastasis." (PMID 38928185, 2024). "During melanoma progression, immunosuppressant stimuli, such as interleukins (IL) IL-8 and IL-10, in the microenvironment can hinder DC maturation and lock DCs in immature phenotypes." (PMID 38426087, 2024). "IL-10 is a potent anti-inflammatory cytokine, which can be produced by many cell types including melanoma cells and Tregs, thereby playing an essential role in dampening the immune responses and inhibiting pro-inflammatory signals." (PMID 38539560, 2024). "Transfer of B1a Bregs in mouse melanoma models has been shown to exacerbate tumor growth, a process thought to be mediated by the secretion of anti-inflammatory factors including IL-10, IL-35 and TGF-β by Bregs." (PMID 38533720, 2024). "HDACi A, developed based on Nexturastat A, has been shown to suppress melanoma tumor growth by inducing an immune response through the downregulation of IL-10." (PMID 39063958, 2024). "Melanoma, multiple myeloma, and lung cancer can secrete IL-10 to inhibit the differentiation of monocytes into DCs and disrupt the antigen-presenting function of DCs." (PMID 38381884, 2024). "For example, HIF-1a in hypoxic melanoma cells induced translocation and secretion of IL-10, which induced macrophage activation to the alternative M2 phenotype." (PMID 36816959, 2023). "The IL-10 secreted in high levels by melanoma promote the trans-differentiation of moDCs into tolerogenic CD14+ BDCA3+ macrophage-like cells similar to the one enriched in melanoma metastases." (PMID 37190135, 2023). "In patients with advanced melanoma, using the anti-PD-1 antibody while inhibiting IL-10 enhanced the cytotoxicity of CD8+ TIL cells." (PMID 36891319, 2023). "In murine melanoma models, IL-10/Fc treatment promoted their self-renewal and improved the effector function by upregulating mitochondrial pyruvate carrier-dependent oxidative phosphorylation." (PMID 37398660, 2023). "It reduces the expression of immunosuppressive genes, including PD-L1 and IL-10, in advanced-stage melanoma patients." (PMID 36900505, 2023).